TLCD4-RWDD3 (TLCD4-RWDD3 readthrough)
Synonyms: TMEM56-RWDD3
Gene: Protein-coding gene on chromosome 1 (95,117,923 to 95,247,225, forward strand). Ensembl gene ENSG00000271092.
Genetic constraint (gnomAD): Loss-of-function variants: 13 observed, 26.09 expected, observed/expected ratio (o/e) 0.5, 90% interval 0.32 to 0.79. The upper end of that interval is the gene's LOEUF score, 0.79, which puts it in group 3 of 6, group 1 being the genes least tolerant of losing a copy. Missense variants: 203 observed, 226.04 expected, observed/expected ratio (o/e) 0.9, 90% interval 0.8 to 1.01. Synonymous variants: 82 observed, 82.58 expected, observed/expected ratio (o/e) 0.99, 90% interval 0.83 to 1.19.